TAF11L3 (TATA-box binding protein associated factor 11 like 3)
Gene: Protein-coding gene on chromosome 5 (17,518,367 to 17,518,963, forward strand). Ensembl gene ENSG00000284439.
Gene Ontology:
Molecular function: RNA polymerase II general transcription initiation factor activity; protein heterodimerization activity
Biological process: RNA polymerase II preinitiation complex assembly; transcription initiation at RNA polymerase II promoter
Cellular component: transcription factor TFIID complex; nucleus
Homologues: Orthologues: tropical clawed frog taf11 (45% identical), zebrafish taf11 (44% identical), Drosophila melanogaster Taf11 (42% identical), Caenorhabditis elegans taf-11.1 (33% identical), Caenorhabditis elegans taf-11.2 (27% identical). Paralogues in human: TAF11L10 (99% identical), TAF11L5 (99% identical), TAF11L6 (99% identical), TAF11L7 (99% identical), TAF11L8 (99% identical), TAF11L4 (99% identical), TAF11L9 (99% identical), TAF11L13 (94% identical), TAF11L2 (91% identical), LINC02218 (87% identical), TAF11L12 (87% identical), TAF11L11 (84% identical), and 2 more.